RN7SL471P (RNA, 7SL, cytoplasmic 471, pseudogene)
Synonyms: RN7SL257P
Gene: Miscellaneous RNA gene on chromosome 6 (28,977,475 to 28,977,773, forward strand). Ensembl gene ENSG00000263426.
Homologues: Orthologues: chimpanzee Metazoa_SRP (99% identical), macaque Metazoa_SRP (97% identical), rabbit Metazoa_SRP (94% identical), pig Metazoa_SRP (88% identical). Paralogues in human: RN7SL2 (74% identical), RN7SL1 (73% identical), RN7SL3 (72% identical), RN7SL300P (67% identical), RN7SL493P (67% identical), RN7SL357P (67% identical), RN7SL769P (67% identical), RN7SL296P (66% identical), RN7SL301P (66% identical), RN7SL492P (66% identical), RN7SL668P (66% identical), RN7SL15P (66% identical), and 696 more.